H2BC8 (H2B clustered histone 8)
Description:
Core component of nucleosome. Nucleosomes wrap and compact DNA into chromatin, limiting DNA accessibility to the cellular machineries which require DNA as a template. Histones thereby play a central role in transcription regulation, DNA repair, DNA replication and chromosomal stability. DNA accessibility is regulated via a complex set of post-translational modifications of histones, also called histone code, and nucleosome remodeling. Has broad antibacterial activity. May contribute to the formation of the functional antimicrobial barrier of the colonic epithelium, and to the bactericidal activity of amniotic fluid.
Synonyms: H2B/a; H2BC4; H2BFA; HIST1H2BG; H2B.1A; H2BC10; H2BC6; H2BC7; dJ221C16.8
Gene: Protein-coding gene on chromosome 6 (26,216,200 to 26,216,688, reverse strand). Ensembl gene ENSG00000273802.
Subcellular location: Nucleus; Chromosome
Subcellular location (Human Protein Atlas): Nucleoplasm; Cytosol
Pathways (Reactome):
Gene expression (Transcription): B-WICH complex positively regulates rRNA expression; DNA methylation; ERCC6 (CSB) and EHMT2 (G9a) positively regulate rRNA expression; MLL4 and MLL3 complexes regulate expression of PPARG target genes in adipogenesis and hepatic steatosis; NoRC negatively regulates rRNA expression; PRC2 methylates histones and DNA; RNA Polymerase I Promoter Escape; RNA Polymerase I Promoter Opening; RUNX1 regulates genes involved in megakaryocyte differentiation and platelet function; RUNX1 regulates transcription of genes involved in differentiation of HSCs; Regulation of endogenous retroelements by KRAB-ZFP proteins; Regulation of endogenous retroelements by Piwi-interacting RNAs (piRNAs); Regulation of endogenous retroelements by the Human Silencing Hub (HUSH) complex; SIRT1 negatively regulates rRNA expression; Transcriptional regulation by small RNAs
Chromatin organization: CHD1 and CHD2 subfamily; CHD6, CHD7, CHD8, CHD9 subfamily; ChAHP complex assembly; HATs acetylate histones; HDACs deacetylate histones; Interaction of NuRD complexes with transcription factors; NuRD complex assembly
DNA Repair: Cleavage of the damaged purine; Cleavage of the damaged pyrimidine; Nonhomologous End-Joining (NHEJ); Processing of DNA double-strand break ends; Recognition and association of DNA glycosylase with site containing an affected purine; Recognition and association of DNA glycosylase with site containing an affected pyrimidine; Recruitment and ATM-mediated phosphorylation of repair and signaling proteins at DNA double strand breaks
Cell Cycle: Condensation of Prophase Chromosomes; Deposition of new CENPA-containing nucleosomes at the centromere; G2/M DNA damage checkpoint; Inhibition of DNA recombination at telomere; Packaging Of Telomere Ends
Developmental Biology: Activation of anterior HOX genes in hindbrain development during early embryogenesis; Chromatin modifications during the maternal to zygotic transition (MZT); Replacement of protamines by nucleosomes in the male pronucleus; Transcriptional regulation of granulopoiesis
Disease: Defective pyroptosis; Dengue Virus-Host Interactions
and 18 more pathways
Gene Ontology:
Molecular function: identical protein binding; protein binding; DNA binding; structural constituent of chromatin; protein heterodimerization activity
Biological process: antibacterial humoral response; antimicrobial humoral immune response mediated by antimicrobial peptide; defense response to Gram-positive bacterium; innate immune response in mucosa; chromatin organization; nucleosome assembly
Cellular component: extracellular exosome; extracellular region; nucleus; nucleoplasm; nucleosome; chromosome
Genetic constraint (gnomAD): Loss-of-function variants: 11 observed, 6.71 expected, observed/expected ratio (o/e) 1.64, 90% interval 0.97 to 1.95. That is too few expected variants to judge how well the gene tolerates losing a copy. Missense variants: 195 observed, 176.48 expected, observed/expected ratio (o/e) 1.1, 90% interval 0.98 to 1.24. Synonymous variants: 150 observed, 70.39 expected, observed/expected ratio (o/e) 2.13.
Homologues: Orthologues: chimpanzee H2BC4 (100% identical). Paralogues in human: H2BC10 (100% identical), H2BC4 (100% identical), H2BC6 (100% identical), H2BC7 (100% identical), H2BC12 (99% identical), H2BC15 (99% identical), H2BC21 (99% identical), H2BC5 (99% identical), H2BC9 (99% identical), H2BC11 (98% identical), H2BC13 (98% identical), H2BC17 (98% identical), and 9 more.
Diseases named in the same sentence as H2BC8 in open-access papers:
H2BC8 is named in the same sentence as 1 disease in open-access papers, as found by Europe PMC text mining. Sharing a sentence is not in itself a finding about the gene and the disease. The quoted sentences say what the papers report.
cancer (1 paper, 2023). A tumor composed of atypical neoplastic, often pleomorphic cells that invade other tissues. "Intriguingly, H3-3A and H1-4 mutations were mutually exclusive across cancers, whereas H2BC8 and H2AC15 significantly co-occurred." (PMID 37640703, 2023).